BOK-AS1 (BOK antisense RNA 1)
Synonyms: NCRNA00151; NAToB; LOC105373974; formerly BOKAS
Gene: Long non-coding RNA gene on chromosome 2 (241,544,401 to 241,558,977, reverse strand). Ensembl gene ENSG00000234235.
Diseases named in the same sentence as BOK-AS1 in open-access papers:
BOK-AS1 is named in the same sentence as 1 disease in open-access papers, as found by Europe PMC text mining. Sharing a sentence is not in itself a finding about the gene and the disease.
BOK-AS1 shares sentences with these, for which no sentence is quoted: cancer (1 paper).